DLL3 (delta like canonical Notch ligand 3)
Diseases named in the same sentence as DLL3 in open-access papers (continued):
Sharing a sentence is not in itself a finding about the gene and the disease.
lymph node metastasis (6 papers, 2020 to 2025). "Moreover, DLL3 expression has already been associated with the presence of desmoplasia and lymph node metastases, as confirmed by our results." (PMID 38958823, 2024). "However, other studies have associated high DLL3 expression with the smoking history of patients and higher prevalence in patients with lymph node metastasis." (PMID 38468968, 2024). "However, current knowledge on DLL3 and UCEC is limited to a single study analyzing the cancer genome atlas (TCGA) database, which suggests that DLL3 overexpression and advanced tumor stage, grade, and lymph node metastasis are independent prognostic predictors for EC." (PMID 40066092, 2025). "Tumors exhibiting desmoplasia and lymph node metastasis (≥50%) demonstrated high DLL3 expression, whereas non-desmoplastic specimens showed low DLL3 levels." (PMID 41200177, 2025). "There was no marked difference in the sex, smoking status, surgical procedure, pathological stage, pathological tumor size, or rate of lymph node metastasis, pleural invasion, or vascular invasion between the patients with DLL3 expression‐positive and expression‐negative LCNEC." (PMID 32691982, 2020).
ovarian carcinoma (6 papers, 2017 to 2025). A malignant neoplasm originating from the surface ovarian epithelium. "In addition, NOTCH2, NOTCH3, DLL3, MAML1, and ADAM17 were determined as the five most relevant genes in ovarian cancer." (PMID 35136410, 2022).
lung neuroendocrine tumors (5 papers, 2017 to 2025). "In conclusion, our study demonstrated a high prevalence of DLL3 expression in high-grade lung NET patients and its association with aggressive clinicopathological features." (PMID 34568063, 2021). "However, DLL3 prevalence in lung NETs and its association with clinicopathological characteristics and prognosis remained unclear." (PMID 34568063, 2021). "However, despite these limitations, our study demonstrated a high prevalence of DLL3 expression in high-grade lung NET patients and its association with aggressive clinicopathological features." (PMID 34568063, 2021). "Well-differentiated lung NETs (n = 11) frequently expressed DLL3, with nine tumors (81.8%) showing positivity ranging from 5 to 100% of tumor cells (average H-score 191; range 5–300)." (PMID 40699376, 2025). "Bispecific antibodies targeting DLL3 have been used for pulmonary neuroendocrine neoplasms, and a similar bispecific antibody approach has been used to target SEZ6." (PMID 40699376, 2025). "For these reasons, recent studies have focused on the immunohistochemical DLL3 expression in lung NETs." (PMID 34568063, 2021). "In this study, we analyzed the immunohistochemical expression of DLL3 in a cohort of 155 patients with lung NETs including TCs, ACs, SCLCs, and LCNECs." (PMID 34568063, 2021). "A recent study revealed that high-grade pulmonary neuroendocrine tumor-initiating cells in mice can be targeted with and also eradicated by a Dll3 antibody-drug conjugate." (PMID 28482837, 2017). "Only Xie and collaborators observed a significant association between high DLL3 expression and better OS and small size of tumors in both SCLC and AC patients, suggesting that the DLL3 expression might represent a favorable prognostic factor in lung NETs." (PMID 34568063, 2021). "In this context, DLL3 expression could add useful prognostic information to histological subtyping in low-grade lung NETs." (PMID 34568063, 2021).
small cell bladder cancer (5 papers, 2020 to 2023). "For example, high DLL3 expression was associated with shorter OS and PFS in small cell bladder cancer." (PMID 32847588, 2020). "Moreover, DLL3 was identified in a subset of small cell carcinomas of the bladder as a negative prognostic biomarker, and the in vivo efficacy of a DLL3-targeting conjugated antibody was demonstrated in a PDX model." (PMID 35608806, 2022).
thyroid cancer (5 papers, 2023 to 2025). "Among the remaining 22 cancer types, DLL3 expression was found to be downregulated in thyroid cancer (THCA) but significantly increased in several other cancers compared to adjacent non-tumor tissues." (PMID 40066092, 2025). "Among the 10 thyroid carcinomas, only two poorly differentiated oncocytic carcinomas were weakly positive in 10% of the cells for DLL3 (H-score 10), and only one of those tumors was moderately positive for SEZ6 in 5% of the cells (H-score 10)." (PMID 40699376, 2025). "On the other hands, DLL3 levels were downregulated in thyroid carcinoma and KICH tumors compared to normal tissues (THCA)." (PMID 37179118, 2023). "Additionally, we identified small subsets of DLL3-high tumors in other cancer types, including kidney cancers (7%), thyroid carcinomas (16%), and non-SCLCs (11%)." (PMID 39874041, 2025).
carcinoids (4 papers, 2019 to 2022). "We analyzed the immunohistochemical expression of DLL3 and its prognostic role in a consecutive series of 155 surgically resected lung NETs, including typical carcinoid (TC), atypical carcinoid (AC), LCNEC, and SCLC patients." (PMID 34568063, 2021). "Although to a lower extent as compared with small cell lung carcinoma, high DLL3 expression was observed in 37% of atypical carcinoids and 32.8% of typical carcinoids." (PMID 33641055, 2021). "The supra-carcinoids were negative for DLL3 expression, and had generally high-expression levels of NOTCH1-3." (PMID 31431620, 2019). "Furthermore, we found a correlation between the protein levels of DLL3 and CD1A (Pearson test p-value = 0.00034), providing additional evidence for the existence of a DLL3+ CD1A+ subgroup of carcinoids." (PMID 31431620, 2019). "However, we do not have a straightforward explanation for the DLL3 prevalence discrepancies observed in carcinoid cohorts." (PMID 34568063, 2021). "We identify therapeutically relevant molecular groups of pulmonary carcinoids, suggesting DLL3 and the immune system as candidate therapeutic targets; we confirm the value of OTP expression levels for the prognosis and diagnosis of these diseases, and we unveil the group of supra-carcinoids." (PMID 31431620, 2019).
colon adenocarcinoma (4 papers, 2014 to 2025). "But the role of DLL3 in colon adenocarcinoma (COAD) has not been studied in depth." (PMID 37274780, 2023).
neuroblastoma (4 papers, 2022 to 2025). Neuroblastoma (NB) is the most common solid, extracranial childhood tumor. "Here, we show that the Notch ligand DLL3 is robustly expressed in most high-risk neuroblastoma preclinical models, but much less so in the patient tumor samples." (PMID 36381237, 2022). "We used harmonized RNA-sequencing data to compare DLL3 gene expression of high-risk neuroblastoma primary tumors (n = 126) to other pediatric and adult tumors (n = 1,189) as well as 7859 GTEx samples across 31 unique normal tissues." (PMID 36381237, 2022). "Noting in our RNA-sequencing data that the median DLL3 expression level in neuroblastomas was higher than in SCLC, here we sought to develop DLL3 as an immunotherapeutic target for high-risk neuroblastoma." (PMID 36381237, 2022). "In particular, DLL3 has been tested as a target for rovalpituzumab tesirine therapy in neuroblastoma models with promising results." (PMID 36121500, 2022). "We evaluated DLL3 expression in RNA-sequencing datasets and performed IHC on neuroblastoma patient-derived xenograft (PDX), human neuroblastoma primary tumor and normal childhood tissue microarrays." (PMID 36381237, 2022). "We next optimized an IHC assay using a commercially available anti-DLL3 mAb (Ventana, SP347 clone) to evaluate DLL3 expression in a panel of neuroblastoma PDX models." (PMID 36381237, 2022). "Any neuroblastoma clinical trial must consider the heterogeneity and plasticity of DLL3 expression on Notch pathway activity in this disease." (PMID 36381237, 2022). "In comparison with normal tissues, except for brain, pituitary gland, and testes, DLL3 showed significantly higher expression in neuroblastoma and some other pediatric solid tumors, such as malignant rhabdoid tumor and Wilms tumor." (PMID 36381237, 2022). "A DLL3-targeting ADC showed objective activity only in neuroblastoma models with high DLL3 expression." (PMID 36381237, 2022). "DLL3 protein was robustly expressed across the neuroblastoma PDX array, but membranous staining was variable." (PMID 36381237, 2022). "Here we determine the efficacy of rovalpituzumab tesirine (Rova-T), an antibody–drug conjugated (ADC) with a pyrrolobenzodiazepine dimer toxin targeting DLL3, in preclinical models of human neuroblastoma." (PMID 36381237, 2022). "The efficacy seen with Rova-T against a panel of neuroblastoma PDXs suggests that DLL3 is a potential candidate therapeutic target in this disease." (PMID 36381237, 2022). "We hypothesize that the predominant adrenergic cell type of neuroblastomas must maintain suppression of Notch signaling, and that PDXs are enriched for adrenergic cell type and thus DLL3 overexpression." (PMID 36381237, 2022). "Notably, the median DLL3 expression level in neuroblastomas was higher than in SCLC (n = 79), albeit with a broader range of expression." (PMID 36381237, 2022).
adenoma (3 papers, 2017 to 2023). A neoplasm arising from the epithelium. "The expression level of Dll1, Dll3, Jagged1, Jagged2, Notch3, and Hes5 was similar in the small intestine adenomas and the normal tissue epithelium." (PMID 28086833, 2017). "Comparing the adenomas with the normal WT gut we found that Dll1 and Dll3 lose their expression in the large intestine." (PMID 28086833, 2017). "Unfortunately, DLL3 was not screened at that time, since study was comparing the difference in serum protein level between control, patients with adenoma and colon cancer cases." (PMID 37274780, 2023). "Comparatively, in adenomas, ≥2-fold Notch3 expression was detected in 56% followed by Notch1 (44%), Notch4 (33%), and Notch2 (11%), while for ligand Jag1, mRNA was overexpressed in 33%, Jag2, Dll1, and Dll3 in 11%, whereas Dll4 was not expressed in adenomas." (PMID 32211044, 2020).
colorectal cancer (3 papers, 2020 to 2024). A primary or metastatic malignant neoplasm that affects the colon or rectum. "Jag2 was the most frequently observed ligand that was overexpressed in 52%, while a higher expression of Jag1, Dll1, Dll3, and Dll4 was found in 26%, 25%, 25%, and 39% colorectal cancers, respectively." (PMID 32211044, 2020).
gastric cancer (3 papers, 2022). A primary or metastatic malignant neoplasm involving the stomach. "The protein level of DLL3 was significantly higher (++/+++) in gastric-cancer tissues (21/35) in comparison with that in tumor-adjacent tissues (12/35)." (PMID 35382168, 2022). "Collectively, these data indicated that DLL3 promoted cell proliferation and migration in stomach-cancer cells." (PMID 35382168, 2022). "In vitro experiment have been confirmed DLL3 overexpression can promote the proliferation of gastric cancer cells in vitro, and down-regulation of DLL3 inhibits the proliferation of gastric cancer cells." (PMID 36071128, 2022). "Furthermore, we collected 35 stomach-cancer tissues and corresponding tumor-adjacent tissues to assess DLL3 expression by immunohistochemistry." (PMID 35382168, 2022). "This is evidence that DLL3 regulates macrophages in stomach cancer, suggesting that DLL3 may be a novel and potential target for stomach-cancer therapy." (PMID 35382168, 2022). "These four proteins, including DLL3, IL-33, LG3BP, and HSPA8, could be a new insight into and promising diagnostic or therapeutic targets of stomach cancer." (PMID 35382168, 2022). "The upregulation of DLL3 in stomach cancer could be induced by macrophages." (PMID 35382168, 2022). "However, the effect of DLL3 in stomach cancer is barely understood." (PMID 35382168, 2022). "Our data may shed light on the oncogenic effect of DLL3 on stomach cancer." (PMID 35382168, 2022). "Therefore, potential therapy may depend on the downregulation of the DLL3–Notch pathway to suppress the protumorigenic functions of TAMs in stomach cancer." (PMID 35382168, 2022). "DLL3 was overexpressed or inhibited in MKN45 and BGC823 to further investigate the oncogenic effect of DLL3 on stomach cancer." (PMID 35382168, 2022). "Downregulation of DLL3 increased the percentage of cells in the G0/G1 phase at the expense of the S phase in MKN45 and BGC823, suggesting that DLL3 downregulation decreased G1/S transition in gastric-cancer cells." (PMID 35382168, 2022). "The co-culture of macrophages and stomach-cancer cells MKN45 and BGC823 could enhance cell proliferation accompanied by the activation of Notch1/Notch2 signaling and upregulation of DLL3." (PMID 35382168, 2022). "Moreover, gene expressions of DLL3, IL-33, LG3BP (also LGASLS3BP), and HSPA8 were analysed in UCSC Xena Functional Genomics Explorer based on the TCGA data set from 415 primary tumor samples of stomach cancer and 35 normal tissues." (PMID 35382168, 2022).
Merkel cell carcinomas (3 papers, 2025). "Merkel cell carcinomas (n = 13) expressed DLL3 strongly and diffusely (H-score 178, range 10–300) and 10 of 13 had positivity for SEZ6 (H-score 128)." (PMID 40699376, 2025). "All 13 cases of Merkel cell carcinoma including primary and metastatic disease showed weak to strong DLL3 positivity in 10–100% of cells (average H-score 178, range 10–300)." (PMID 40699376, 2025). "SCNEC (90/112, 80.4%) and Merkel cell carcinoma (13/15, 86.7%) showed a significantly higher frequency of DLL3 expression (any degree; p < 0.001) compared to LCNEC (82/131, 62.6%) and MiNEN (16/56, 28.6%)." (PMID 40153138, 2025).
metastatic prostate carcinoma (3 papers, 2019 to 2024). A carcinoma that arises from the prostate gland and has spread to other anatomic sites. "This fact proposes DLL3 as a possible biomarker of NED and a potential therapeutic target for the treatment of DLL3-positive metastatic prostate cancer." (PMID 31443481, 2019).
osteosarcoma (3 papers, 2018 to 2025). A usually aggressive malignant bone-forming mesenchymal neoplasm, predominantly affecting adolescents and young adults. "On the other hand, EGCG could partially inactivate Notch3/DLL3 signaling cascade targeting SOX2OT variant 7 to reduce the stemness then abated drug-resistance of osteosarcoma cells." (PMID 29475441, 2018). "In osteosarcoma, both in vivo and in vitro experiments indicate that the lncRNA SOX2OT variant seven can activate DLL3/Notch3 signaling, maintaining the stemness and doxorubicin-resistance of tumor cells." (PMID 34195229, 2021). "On the other hand, EGCG could inactivate Notch3/DLL3 signaling targeting SOX2OT variant 7 to reduce the stemness of OS cells and then abated drug-resistance of osteosarcoma cells." (PMID 29475441, 2018). "Treatment of osteosarcoma cells with epigallocatechin gallate, a polyphenol from green tea, can counteract the SOX2OT-7/DLL3/Notch3 axis, thus inhibiting cancer progression." (PMID 34195229, 2021).
pituitary adenomas (3 papers, 2022 to 2025). "Egfl7 could also promote pituitary adenomas proliferation and invasion via the Notch2/DLL3 signaling pathway." (PMID 37480091, 2023).
Alagille syndrome (2 papers, 2007 to 2022). "Notch-associated disorders include different types of severe disorders such as Alagille syndrome caused by mutations in both ligand JAG1 and receptor Notch2 and autosomal recessive spondylocostal dysostosis, caused by mutations in ligand DLL3, and many other members of the Notch-signaling pathway." (PMID 36506336, 2022).
breast invasive carcinoma (2 papers, 2022 to 2023). "The expression of DLL3 on the tumor tissues of patients with invasive breast cancer can promote the infiltration of immune cells, including plasma cells, CD8 T cells, CD44 memory-activated cells, macrophages, and T regulatory cells." (PMID 36428765, 2022).
lung adenocarcinoma (2 papers, 2021 to 2024). A carcinoma that arises from the lung and is characterized by the presence of malignant glandular epithelial cells. "DLL3-positive SCLC tissue was used as a positive control, and DLL3-negative lung adenocarcinoma tissue was used as a negative control." (PMID 39392394, 2024).
lymphoma (2 papers, 2023). A malignant (clonal) proliferation of B- lymphocytes or T- lymphocytes which involves the lymph nodes, bone marrow and/or extranodal sites. "DLL3 expression was associated with MSI in 12 other tumor types, including lymphoma, colorectal, lungs, and stomach malignancies." (PMID 37179118, 2023).
Pancreatic Cancer (2 papers, 2023 to 2024). "Moreover, it has been found that DLL3 is associated with various solid malignancies, including lung, liver, and pancreatic cancer." (PMID 39759138, 2024). "Although the location of DLL3 expression on the pancreatic cancer cell is still unclear, its absence results in growth inhibition This finding warrants further investigation on this molecule as a druggable target in PaCa." (PMID 39759138, 2024).
pancreatic NETs (2 papers, 2025). "DLL3 was negative in nine of 11 pancreatic NETs; two grade 3 pancreatic NETs had variable weak positivity (H-score 5)." (PMID 40699376, 2025). "Well-differentiated pancreatic NETs (n = 11) were largely DLL3-negative, with two G3 NETs showing focal weak positivity in 5% of the tumor cells (H-score 50 for both tumors)." (PMID 40699376, 2025).
renal cell carcinoma (2 papers, 2014 to 2025). "Further survival data analysis of cancer types with significant changes in expression revealed that the expression level of DLL3 was significantly associated with overall survival (OS) in patients with renal cell carcinoma (KIRC) and UCEC, as indicated by Log-rank tests." (PMID 40066092, 2025).
retinoblastoma (2 papers, 2015 to 2016). A malignant tumor that originates in the nuclear layer of the retina. "Expression of ACOT7 and DLL3 was observed in a majority of retinoblastomas available for analysis, and were also expressed in retinal tissues (n = 5)." (PMID 26379276, 2015). "From within this cohort, we observed that ACOT7 and DLL3 are positively expressed in each retinoblastoma tumor evaluated, in addition to adjacent retina." (PMID 26379276, 2015). "To establish clinical relevance of ACOT7 and DLL3, we performed immunohistochemistry on four human pediatric retinoblastomas representing individual patients." (PMID 26379276, 2015). "From these observations, it is plausible that as retinoblastoma progresses, overexpression of DLL3 and ACOT7 could be characteristic features." (PMID 26379276, 2015). "Among the most downregulated mRNAs in Y79 cells, ACOT7 and DLL3 represent novel therapeutic targets for future retinoblastoma studies, which we found to be expressed in primary retinoblastomas and retinas, and overexpressed in retinoblastoma cell lines as compared to normal retinas." (PMID 26379276, 2015). "To improve our understanding of miRNA-31 and/or -200a mediated regulation in retinoblastoma cells, we also evaluated the extent of repression of STK40, PPP6C, and DLL3 in Weri1 cells to determine if these miRNA-mRNA interactions remained intact." (PMID 26379276, 2015). "In contrast to the first siRNA targeting DLL3, we observed a significant increase (+17%) in Weri1 cell proliferation, which could suggest that expression of DLL3 and proliferation are inversely correlated in a phenotypically less aggressive retinoblastoma cell line." (PMID 26379276, 2015). "Furthermore, our work is the first to demonstrate that overexpression of miRNA-31 and/or miR-200a results in differential gene expression patterns of ACOT7, DLL3, PPP6C, and STK40 between two phenotypically different retinoblastoma cell lines." (PMID 26379276, 2015). "Among the DLL ligands, DLL4 mRNA appeared to be highly expressed in both retinoblastoma lines, compared to DLL1 and DLL3, and it was also highly expressed in the non-neoplastic adult retina." (PMID 27661116, 2016).